HTT (huntingtin)
Diseases named in the same sentence as HTT in open-access papers (continued):
Sharing a sentence is not in itself a finding about the gene and the disease.
Huntington disease (continued). "Huntington’s disease is caused by a triplet expansion in the Huntingtin (HTT) gene." (PMID 33747035, 2021). "Here, we generated and characterized an immune deficient and xeno‐tolerant mouse model of Huntington's disease with the human mutated HTT gene by cross‐breeding the NOD.Cg‐PrkdcscidIl2rγtm1Wgl/SzJ (NSG) mouse, a well‐known immune deficient model, with YAC128 mice." (PMID 33710799, 2021). "Neurons and other cells respond to mutations in the huntingtin gene by turning the activities of other genes up or down, but it is not clear whether all of these changes contribute to the damage seen in Huntington's disease." (PMID 33871358, 2021). "Huntington’s disease (HD) is a major neurodegenerative disorder in humans, involving involuntary body movements and dementia in the later stages, which is caused by the mutation of a gene, huntingtin (HTT)." (PMID 34066037, 2021). "Huntington’s disease (HD) is a multi-system disorder that is caused by expanded CAG repeats within the exon-1 of the huntingtin (HTT) gene that translate to the polyglutamine stretch in the HTT protein." (PMID 34207177, 2021). "This type of mutation in the HTT gene is responsible for Huntington’s disease (HD)." (PMID 32696070, 2021). "Huntington’s disease (HD) is an autosomal-dominant neurodegenerative disorder caused by a CAG-repeat expansion in exon 1 of the huntingtin gene (HTT) and results from expression of mutant huntingtin protein (mHTT) which misfolds in neurons and microglial cells." (PMID 33989290, 2021). "Huntington’s disease (HD) is the most common monogenic neurodegenerative disorder caused by an abnormal CAG trinucleotide repeat expansion within exon 1 of the gene encoding for the huntingtin (HTT) protein." (PMID 34681268, 2021). "LDs were also observed in the striatal tissue of patients with Huntington’s disease (HD) and in primary striatal neurons from a mouse model of HD, an inherited neurodegenerative disorder caused by a defective HTT gene encoding huntingtin that affects movement, behavior, and cognition." (PMID 35052526, 2021). "Huntington’s disease (HD) is a monogenic neurodegenerative disease caused by the mutation encoding for an abnormal trinucleotide that leads to glutamine (CAG) expansion at the Huntingtin (HTT) protein." (PMID 34335276, 2021). "Huntington's disease (HD) is an autosomal dominant neurodegenerative disorder caused by a CAG repeat expansions in the huntingtin gene resulting in the synthesis of a misfolded form of the huntingtin protein (mHTT) which is toxic." (PMID 31997581, 2020). "Huntingtin (Htt) poly-glutamine expansion is a hallmark of Huntington’s disease." (PMID 33013322, 2020). "Huntington’s disease is a familial progressive neurodegenerative disease caused by an autosomal dominant mutation in the huntingtin gene that produces a protein, named huntingtin, whose function remains unclear." (PMID 31947609, 2020). "Huntington’s disease (HD) is an autosomal dominant neurodegenerative disorder caused by an expanded cytosine-adenine-guanine (CAG) trinucleotide repeat in the Huntingtin (HTT) gene." (PMID 33395988, 2020). "Huntington’s disease (HD) is caused by CAG repeat expansion in the huntingtin gene." (PMID 32424160, 2020). "This is likewise true for Huntington’s disease (HD), as the mutated huntingtin protein (HTT) has been reported to affect a wide range of epigenetic signatures, including histone modifications (i.e., acetylation, methylation and ubiquitination), and DNA methylation marks." (PMID 34968288, 2020). "Huntington’s disease (HD) is a dominantly inherited neurodegenerative disorder caused by CAG repeat expansion encoding a polyglutamine (polyQ) stretch near the N-terminus of mutant Huntingtin (mHTT)." (PMID 33219289, 2020).
Huntington disease (continued). "Huntington’s disease (HD) is a monogenetic neurodegenerative disorder that is caused by the expansion of a polyglutamine region within the huntingtin (HTT) protein, but there is still an incomplete understanding of the molecular mechanisms that drive pathology." (PMID 33335120, 2020). "Surprisingly, raising cGMP with sildenafil had very similar effects in these zebrafish larvae as rolipram, not only in the tauopathy models but also in a Huntington’s disease model caused by the expression of a huntingtin exon 1 with a highly expanded polyQ sequence." (PMID 32513741, 2020). "Aggregation of huntingtin is believed to be the cause of Huntington’s disease." (PMID 32967102, 2020). "Finally, a high number of pathogenic variants in the gene encoding huntingtin protein (HTT) are the cause for Huntington’s disease." (PMID 33147747, 2020). "Huntington’s disease (HD), a neurodegenerative disease characterized by progressive motor and cognitive dysfunction, is caused by the mutant huntingtin (mHtt) protein, which is encoded by the huntingtin (HTT) gene that has an expanded CAG repeat (> 36) in chromosome 4." (PMID 32158393, 2020). "Huntington disease (HD) is a genetic disorder caused by glutamine-expansion in the huntingtin (mHTT) protein, which affects motor, psychiatric, and cognitive function, but the mechanisms remain unclear." (PMID 32581130, 2020). "Furthermore, Huntington-associated protein 1 (HAP1) interacts with the huntingtin that, when mutated, causes Huntington’s disease (HD); HAP1 reduces full fusion exocytosis by affecting vesicle docking and controlling fusion pore stabilization." (PMID 32178443, 2020). "Huntington’s disease (HD) is a genetically-mediated neurodegenerative disorder where the etiological defect is a mutation in the huntingtin gene (HTT) that alters the structure of the huntingtin protein and initiates a cascade leading to dementia and premature death." (PMID 31759626, 2020). "Huntington’s disease (HD) is an autosomal dominant neurodegenerative disorder caused by pathogenic expansions of the triplet cytosine-adenosine-guanosine (CAG) within the Huntingtin gene." (PMID 33167595, 2020). "Huntington’s disease is an autosomal dominant inherited neurodegenerative disease caused by a CAG trinucleotide expansion encoding polyglutamine (polyQ) at the N-terminus of Huntingtin (HTT)." (PMID 31208099, 2019). "Importantly, the palmitoylation of amyloid precursor protein (APP) and huntingtin are implicated in Alzheimer’s disease and Huntington’s disease pathogenesis, respectively." (PMID 30946007, 2019). "For instance, a decrease in beclin-1 expression leads to accumulation of mutant huntingtin protein in Huntington’s disease (HD) and loss of laforin polyglucosan inclusions in Lafora’s body disease via activation of mTOR (mammalian/mechanistic target of rapamycin) signaling pathway." (PMID 30866990, 2019). "Huntington’s disease is an inherited neurodegenerative disease that severely impacts motor function and often impairs cognition, which is caused by an autosomal dominant mutation in the huntingtin gene that gives rise to a CAG trinucleotide repeat expansion." (PMID 31824256, 2019). "Huntington’s disease similarly exhibits a unique pathology and clinical course and is caused by a triplet repeat expansion in the huntingtin (HTT) gene, whose normal function is also apparently different from any of the genes associated with familial forms of AD or FTLD." (PMID 31788001, 2019). "Similarly, referring to IT15 (huntingtin) as the “gene for Huntington’s Disease” is a shorthand that erroneously implies the gene encodes the disease state." (PMID 33791532, 2019). "Huntington disease (HD) is an autosomal dominant neurodegenerative disorder caused by an expansion of the CAG repeat region in the first exon of the gene encoding the protein huntingtin (Htt)." (PMID 31156395, 2019).
Huntington disease (continued). "Huntington’s disease is an inherited autosomal dominant disease characterized by insoluble aggregation of an abnormally long polyglutamine (also called inclusions) caused by a gain-of-function mutation in the huntingtin gene." (PMID 31191249, 2019). "Huntington’s disease (HD) is an aggressive autosomal dominant neurodegenerative disorder that is caused by a polyglutamine expansion (polyQ > 36) in exon 1 of the human huntingtin (HTT) gene." (PMID 30837611, 2019). "Huntington disease (HD) is an autosomal dominant late-onset neurodegenerative disease caused by an unstable cytosine-adenine-guanine trinucleotide repeat expansion in the huntingtin (HTT) gene." (PMID 31893246, 2019). "Huntington’s disease (HD) is an autosomal dominant progressive neurodegenerative disorder caused by the toxic expansion of CAG trinucleotide repeats at the N-terminus of the Huntingtin gene." (PMID 31920562, 2019). "We conclude that mutant huntingtin may cause abnormal iron homeostatic pathways by increasing IRP1 expression in Huntington’s disease, suggesting potential therapeutic target." (PMID 30002810, 2018). "However, applying SLIC (Sequence-and Ligation—Independent Cloning, a method for sequence-and ligation-independent cloning) in a study on Huntington’s disease, it has been identified that toxicity of huntingtin mutation is modulated via age-regulated GPX6 gene." (PMID 29758013, 2018). "This resulted in a list of 287 proteins, of which the top two hits were Huntingtin (Htt) and sacsin, proteins that when mutated lead to the neurodegenerative diseases Huntington's disease (HD) and autosomal-recessive spastic ataxia of Charlevoix-Saguenay (ARSACS), respectively." (PMID 30072438, 2018). "Huntington’s disease (HD) is genetically caused by mutation of the Huntingtin (HTT) gene." (PMID 30283298, 2018). "However, BDNF transcription mediated by huntingtin, a protein mutated in Huntington’s disease, was reportedly reduced in Huntington’s disease models." (PMID 30356026, 2018). "In animals, these genetic “stutters” within coding sequences have been shown to underlie genetic disorders such as Huntington’s disease where CAG repeat expansion produces longer tracts of glutamines within the huntingtin protein leading to protein instability." (PMID 29736251, 2018). "Huntington’s disease is caused by an abnormally long polyglutamine tract in the huntingtin protein." (PMID 29754822, 2018). "Huntington’s disease (HD) is caused by a monogenic mutation in the gene encoding Huntingtin (HTT)." (PMID 29904030, 2018). "Also, mutation in the huntingtin protein was shown to affect the mitochondrial import into neurons but not into other cells, leading to premature neuronal death in patients with Huntington disease." (PMID 30006346, 2018). "Polyglutamine expansions in the huntingtin gene cause Huntington’s disease (HD)." (PMID 29509900, 2018). "Huntington's Disease (HD) is caused by an abnormality in the HTT gene." (PMID 29685790, 2018). "Huntington's disease (HD) is an autosomal dominant neurodegenerative disorder caused by a trinucleotide expansion in the HD gene, resulting in an extended polyglutamine tract in the protein huntingtin." (PMID 30186318, 2018). "Huntington’s disease (HD) is an autosomal dominant neurodegenerative disease caused by a pathological expansion of CAG repeats (> 36) in the first exon of the gene encoding huntingtin." (PMID 30002810, 2018). "Huntington's disease (HD) is caused by a CAG‐repeat‐expansion in the Huntingtin gene (HTT)." (PMID 29682858, 2018). "Although SK1 is important in astrocytic survival, the astrocytic activity of SK1 may be required for clearing an autophagy substrate, polyQ-expanded mutant huntingtin (mHtt), the protein that causes Huntington’s disease (HD)." (PMID 29743513, 2018). "Mutation in the huntingtin (HTT) gene causes Huntington’s disease (HD)." (PMID 28270748, 2017). "The Huntingtin (HTT) is the protein mutated in Huntington’s disease (HD)." (PMID 28559546, 2017).
Huntington disease (continued). "We aimed to assess whether autophagosome accumulation contributes to the toxicity of mutant huntingtin with expanded polyQ that causes Huntington's disease, in Huntington's disease cell models." (PMID 28673965, 2017). "It is known abnormality of HTT protein modification is associated with Huntington's disease (HD)." (PMID 29021212, 2017). "Huntington disease is a late-onset neurodegenerative disease, characterized by specific mutations in the polyglutamine trait (poliQ expansion) contained in the first exon of the huntingtin protein." (PMID 28670265, 2017). "Huntington's disease (HD) is a dominantly inherited neurodegenerative disorder caused by the pathological expansion of a trinucleotide (CAG) repeat in the gene that codes for huntingtin (HTT)." (PMID 28993428, 2017). "Huntington's disease (HD) is caused by a genetically mutated huntingtin (mHtt) protein with expanded polyQ stretch, which impairs cytosolic sequestration of the repressor element‐1 silencing transcription factor (REST), resulting in excessive nuclear REST and subsequent repression of neuronal genes." (PMID 28524599, 2017). "Huntington’s disease (HD) is an autosomal-dominant neurodegenerative disorder caused by an expansion of the cytosine-adenine-guanine (CAG) trinucleotide repeat encoding a polyglutamine (polyQ) tract in the amino-terminal region of Huntingtin (Htt) protein." (PMID 28337125, 2017). "Huntington’s disease (HD) is an autosomal dominantly inherited neurodegenerative disorder caused by expanded CAG trinucleotide repeats (>36) in exon 1 of HTT gene that encodes huntingtin protein." (PMID 28674491, 2017). "Huntington’s disease (HD) is an inherited autosomal dominant neurodegenerative disorder caused by the abnormal expansion of a CAG trinucleotide sequence at the N-terminal of the exon 1 of the Huntingtin (HTT) gene located at chromosome 41." (PMID 28336929, 2017). "The polyglutamine expansion in huntingtin protein causes Huntington’s disease." (PMID 27003594, 2016). "Huntington’s disease (HD) is caused by an expansion of the trinucleotide poly (CAG) tract located in exon 1 of the huntingtin (Htt) gene leading to progressive neurodegeneration in selected brain regions, and associated functional impairments in motor, cognitive, and psychiatric domains." (PMID 26859386, 2016). "Huntington’s disease (HD) is an autosomal dominant, progressive neurodegenerative disease caused by an expanded polyglutamine (polyQ) tract in the N-terminal region of mutant huntingtin (mHtt)." (PMID 27147961, 2016). "Mutations in the gene that encodes a protein called huntingtin cause Huntington’s disease." (PMID 27003594, 2016). "It has been reported that the SIRT1 agonist resveratrol protects C. elegans neurons expressing a fragment of the Huntington disease-associated protein huntingtin and mammalian neurons from mutant polyglutamine cytotoxicity in a HdhQ111 knock-in mouse model of Huntington disease." (PMID 27790141, 2016). "Huntington's disease is caused by a polyglutamate expansion of the protein huntingtin." (PMID 27144051, 2016). "Huntington's disease (HD) is an autosomal dominant neurodegenerative disorder caused by the expansion of a CAG codon repeat region in the HTT gene's first exon that results in huntingtin protein aggregation and neuronal cell death." (PMID 27458341, 2016). "Huntington's disease (HD) is a hereditary neurodegenerative disorder caused by the expansion of CAG repeat in the gene encoding huntingtin, a protein of unknown function, with the consequent expansion of polyglutamine tract in this gene product." (PMID 26635623, 2015). "Huntington’s disease (HD) is caused by a CAG repeat expansion in the huntingtin (HTT) gene." (PMID 26218986, 2015). "Finally, we found that SK1 and S1PL regulate the degradation of mutant huntingtin, the protein that causes Huntington’s disease (HD), thus demonstrating a role for the S1P in a relevant and highly penetrant neurodegenerative phenotype." (PMID 26477494, 2015).
Huntington disease (continued). "Moreover, SPAG was found to affect aggregation of Huntingtin (HTT), the protein that causes Huntington disease when its polyQ domain is expanded." (PMID 26068245, 2015). "Huntington’s disease (HD) is an autosomal dominant neurodegenerativedisease caused by an increased number of repeats encoding glutamine in thefirst exon of protein-coding in the huntingtin gene." (PMID 25558393, 2014). "In contrast to mutant SOD1 and Parkin aggregates, COMMD1 has no clear effect on the aggregation of a fragment encoding the N-terminal region of exon 1 of the Huntingtin gene with either 74 or 119 glutamine repeats (HttQ74 and HttQ119) associated with Huntington’s disease." (PMID 24691167, 2014). "Huntington’s disease (HD) is an autosomal dominant neurodegenerative disorder that is caused by a polyglutamine (polyQ) repeat expansion at the N-terminus of the protein huntingtin (HTT)." (PMID 25368120, 2014). "Huntington's disease (HD) is a neurodegenerative disorder characterized by progressive motor, cognitive and psychiatric deficits, associated with predominant loss of striatal neurons and is caused by polyglutamine expansion in the huntingtin protein." (PMID 24587280, 2014). "Huntington's disease (HD) is a genetic neurodegenerative condition resulting from the expansion of a polyglutamine (polyQ) encoding region within exon 1 of the huntingtin gene (HTT;)." (PMID 25464275, 2014). "In Huntington disease, mutations in huntingtin (which normally undergoes different PTMs, such as phosphorylation, SUMOylation, ubiquitination, acetylation, proteolytic cleavage, and palmitoylation) significantly alters PTMs leading to changes in the clinical phenotype." (PMID 25988147, 2014). "Although the progression of Huntington’s disease is linked to toxic accumulation of mutant huntingtin protein, loss of wild-type huntingtin function might also contribute to neuronal cell death, but its precise function is not well understood." (PMID 25368120, 2014). "Huntington's disease (HD) is an autosomal dominant neurodegenerative disorder caused by CAG repeat expansions in the huntingtin gene (htt) that result in an increased number of glutamine residues in the huntingtin protein (polyglutamine expansion)." (PMID 24824433, 2014). "Huntington’s disease (HD) is an autosomal dominant neurodegenerative disorder that is caused by the expression of mutant huntingtin secondary to a polyglutamine (CAG) expansion in exon 1 of the huntingtin gene." (PMID 24564568, 2014). "Furthermore, cysteine oxidation of the mutant huntingtin protein that causes Huntington's disease (HD) promotes the formation of stable oligomers." (PMID 24424024, 2014). "In the present communication, we probe whether gain or loss of interactions of mutant Huntingtin protein (HTT) that causes Huntington's disease (HD) can explain functional abnormalities observed in HD." (PMID 23741403, 2013). "In Huntington’s disease, a mutated version of the huntingtin protein leads to cell death." (PMID 23853712, 2013). "We hypothesised that it may be involved in the molecular pathogenesis of Huntington's disease (HD), a protein-folding neurodegenerative disorder caused by an aggregation-prone polyglutamine expansion in the huntingtin protein." (PMID 24302884, 2013). "In particular, Parkinson's disease-specific proteins associated with fission/fusion include PTEN-inducible kinase 1/parkin, alpha-synuclein, and HTRA2/OMI, while mutant huntingtin appears to be associated with alterations in mitochondrial fission and fusion in Huntington's disease." (PMID 23468624, 2013). "Huntington’s disease (HD) is caused by the expansion of a CAG repeat in the huntingtin (HTT) gene." (PMID 23593159, 2013). "The reduction of pre-enkephalin (pENK) mRNA expression might be an early sign of striatal neuronal dysfunction in Huntington’s disease (HD), due to mutated huntingtin protein." (PMID 24040390, 2013).